DPY19L4 (dpy-19 like 4)
Description:
Probable C-mannosyltransferase that mediates C-mannosylation of tryptophan residues on target proteins.
Tractability: Antibody: UniProt predicts a signal peptide or a membrane-spanning region. PROTAC: ubiquitination databases record sites on it.
Gene: Protein-coding gene on chromosome 8 (94,719,703 to 94,793,836, forward strand). Ensembl gene ENSG00000156162.
Subcellular location: Membrane
Subcellular location (Human Protein Atlas): Vesicles
Gene Ontology:
Molecular function: protein binding; mannosyltransferase activity
Cellular component: endoplasmic reticulum membrane; membrane
Genetic constraint (gnomAD): Loss-of-function variants: 76 observed, 76.81 expected, observed/expected ratio (o/e) 0.99, 90% interval 0.82 to 1.2. The upper end of that interval is the gene's LOEUF score, 1.2, which puts it in group 5 of 6, group 1 being the genes least tolerant of losing a copy. Missense variants: 664 observed, 688.35 expected, observed/expected ratio (o/e) 0.96, 90% interval 0.9 to 1.03. Synonymous variants: 213 observed, 226.65 expected, observed/expected ratio (o/e) 0.94, 90% interval 0.84 to 1.05.
Homologues: Orthologues: chimpanzee DPY19L4 (99% identical), macaque DPY19L4 (99% identical), dog DPY19L4 (96% identical), pig DPY19L4 (94% identical), rabbit DPY19L4 (90% identical), mouse Dpy19l4 (89% identical), rat Dpy19l4 (88% identical), guinea pig DPY19L4 (85% identical), tropical clawed frog dpy19l4 (69% identical), Drosophila melanogaster CG6659 (19% identical). Paralogues in human: DPY19L3 (42% identical), DPY19L1 (24% identical), DPY19L2 (24% identical).
Diseases named in the same sentence as DPY19L4 in open-access papers:
DPY19L4 is named in the same sentence as 2 diseases in open-access papers, as found by Europe PMC text mining. Sharing a sentence is not in itself a finding about the gene and the disease.
DPY19L4 shares sentences with these, for which no sentence is quoted: Hypertension (1 paper); metabolic syndrome (1).